MFN2 (mitofusin 2)
Diseases named in the same sentence as MFN2 in open-access papers (continued):
Sharing a sentence is not in itself a finding about the gene and the disease.
optic atrophy (32 papers, 2006 to 2026). A disorder characterized by loss of optic nerve fibers. "In yeast overexpression systems, SLC25A46 interacts with mitofusin 2 (MFN2) and optic atrophy 1 (Opa1) genes which are associated with CMT2A (MFN2) and optic atrophy (Opa1)." (PMID 40428407, 2025). "In this regard, MFN2 variants linked to mtDNA alterations are found in patients with optic atrophy, such as the D210V variant and the D414V variant." (PMID 35399520, 2022). "Here, in a patient presenting with ataxia, sensorineural hearing loss, and optic atrophy leading to vision loss, we report the presence of a homozygous novel candidate pathogenic variant in MFN2, p.(D414V), located in the middle of the HR1 domain." (PMID 38274408, 2021). "A syndromic form of optic atrophy reminiscent of DOA plus can arise from dominant mutations in the MFN2 gene, which encodes for a mitochondrial outer membrane protein." (PMID 27696015, 2016). "Instead, mutations clustered predominantly in the Mfn2 GTPase domain cause hereditary Charcot Marie Tooth syndrome type 2a and atypical forms of optic atrophy." (PMID 22957060, 2012). "In addition to peripheral neuropathy, patients with MFN2 variants can sometimes also present with additional phenotypes, including optical atrophy, sensorineural hearing loss, cerebellar ataxia and multiple systemic lipomatosis, to name a few." (PMID 35399520, 2022). "Notably, the patient phenotypes described here with the MFN2-D414V variant are reminiscent of variants inOPA1, where patients also have optic atrophy, hearing loss and ataxia." (PMID 38274408, 2021). "Interestingly, no alterations were found in HMSN VI families screened for OPA1, the gene more strictly associated with optic atrophy, whereas defects and de novo mutations were identified in MFN2." (PMID 23781337, 2013). "MFN2 could be associated with Charcot–Marie–Tooth disease type 2A and optic atrophy." (PMID 34573359, 2021). "Optic atrophy beginning in early childhood followed by adult-onset axonal neuropathy and mitochondrial myopathy without external ophthalmoplegia was the main clinical features described in a Tunisian family carrying the novel MFN2 missense mutation c.629A>T (p.D210V)." (PMID 23781337, 2013). "The reported yield of nuclear and mitochondrial DNA sequencing in bilateral optic atrophy is around 20% and includes pathogenic variants in the OPA1, mtDNA genes, or rarely WFS1, MFN2, POLG, ACO2, and DNAJC30 genes." (PMID 36294366, 2022). "Mutations in MFN2 and OPA1 cause MDDS, presenting as optic atrophy, myopathy, axonal neuropathy and Charcot–Marie–Tooth disease in the case of MFN2 and optic atrophy and Behr syndrome in the case of OPA1." (PMID 34208592, 2021). "Mutations of the Mfn2 gene have also been implicated in Hereditary Motor and Sensory Neuropathy type VI (HMSN VI), a form of CMT associated with optic atrophy." (PMID 32455165, 2020). "Certain human mutations in mitofusin 2 (MFN2) and optic atrophy protein 1 (OPA1) cause disease phenotypes, such as peripheral neuropathy and optic atrophy, which are often also associated with mtDNA depletion." (PMID 31170154, 2019). "This is further supported by the close association of mutations in MFN2 and OPA1 with Charcot–Marie–Tooth disease and optic atrophy, respectively, while disease as a direct consequence of DRP1 mutation occurs far less frequently." (PMID 30840087, 2019). "Conversely, why is it that only some patients with MFN2 and SPG7 mutations develop visual failure and optic atrophy?" (PMID 21112411, 2011). "Recently, mutations in MFN2 have also been linked to two rare forms of hereditary neuropathy, namely HMSN V (with pyramidal signs) and HMSN VI (with optic atrophy)." (PMID 16762064, 2006). "Although not common, some MFN2 variants are linked to other disease phenotypes such as optic atrophy." (PMID 38274408, 2021).
optic atrophy (continued). "The patient showed no symptom of optic atrophy which is a characteristic of CMT6A caused by MFN2 mutations until the time of the first examination (7 years old)." (PMID 34193129, 2021). "Mutations in MFN2 cause the axonal form of Charcot–Marie–Tooth neuropathy (CMT2A), either with dominant or recessive transmission and with the co-occurrence in some cases of optic atrophy." (PMID 33806088, 2021). "MFN2 mutations cause CMT peripheral neuropathy, with co-occurrence of optic atrophy." (PMID 33806088, 2021). "The phenotypes with MFN2 variants can be quite variable, including intellectual disability, optic atrophy, auditory impairment, spinal atrophy with or without hydromyelia, and hydrocephalus." (PMID 32532879, 2020). "Mutations in Mfn2 are primarily causal for CMT2A, but have also been reported to cause hereditary motor and sensory neuropathy VI (HMSN VI), which is an axonal neuropathy with optic atrophy." (PMID 29068134, 2018). "Patients with MFN2 p.Arg364Trp showed an early onset of the severe phenotype with optic atrophy." (PMID 28660751, 2017). "None of the patients with a MFN2 mutation had optic atrophy nor were they categorized as very severely affected." (PMID 24053775, 2013). "Missense mutations of Mfn2 are the most common recognized genetic defect for the human neurodegenerative condition Charcot-Marie Tooth Syndrome type 2A (CMT2), and are a rare cause of Optic Atrophy (OA)." (PMID 22957060, 2012). "Additional phenotypes found in patients with MFN2 variants include intellectual disability, optic atrophy (HMSN6), vocal cord palsy, spinal atrophy with or without hydromyelia, and hydrocephalus, all of which support the presence of central nervous system (CNS) involvement in CMT2A2." (PMID 32532879, 2020). "Only one patient with MFN2 p.Leu710Pro mutation showed HMSN with significant spasticity and increased patellar tendon reflex, which is the HMSN V phenotype, while four patients with MFN2 p.Arg104Trp, p.Arg104Leu, and p.Arg364Trp mutations showed HMSN with optic atrophy." (PMID 28660751, 2017). "In addition to the loss of peripheral nerve function, a subset of patients with CMT2A have optic atrophy, suggesting that aberrations in OPA1 and Mfn2 converge on a common pathway that can lead to overlapping clinical outcomes causing optic nerve degeneration." (PMID 29068134, 2018).
cardiomyopathy (31 papers, 2012 to 2025). A disease of the heart muscle or myocardium proper. "Mfn2 T105M and M376V knock-in mice were recently described in the context of a cardiomyopathy caused by the human MFN2 mutation R400Q; neurologic phenotypes of these mice were not reported." (PMID 39284622, 2024). "A largely overlooked, very rare MFN2 mutation, MFN2 R400Q, was over-represented in cardiomyopathy among individuals of African descent." (PMID 37910431, 2023). "By contrast, impaired mitophagy seems to underlie developmental and senescent cardiomyopathies provoked by Mfn gene ablation or engineered MFN2 mutant expression." (PMID 37910431, 2023). "For MFN2 R400Q, the genetic association between this mitophagy-modifying mutation and human cardiomyopathy is intriguing." (PMID 37910431, 2023). "MFN2 dysfunction has been implicated in mitophagy, unfolded protein responses, and the metabolic dysregulation characteristics of neurodegeneration, cardiomyopathy, and cancer." (PMID 37237858, 2023). "The knocking out of MFN2 in old cardiomyocytes alone only caused a mild form of cardiomyopathy but showed better recovery after reperfusion injury." (PMID 33540894, 2021). "Conversely, total cardiac knockout of Mfn1, and one Mfn2 allele, leaving only one functional Mfn2 allele, evoked severe cardiomyopathy at baseline." (PMID 33392184, 2020). "Hearts deficient in both Mfn1 and Mfn2 protected against acute myocardial infarction, cardiomyopathy and sudden cardiac death." (PMID 28941171, 2017). "We believe that these data establish a powerful rationale for targeted genetic discovery and linkage analysis of Mfn2 HR1 mutations in heritable human cardiomyopathies with an unidentified genetic component." (PMID 22957060, 2012). "Results of genetic screening for MFN2 mutations in adult cardiomyopathy." (PMID 37910431, 2023). "However, previous research showed that experimentally disrupting the programmed removal of mitochondria, a process also regulated by mitofusin 2, can cause heart muscle disease known as cardiomyopathy." (PMID 37910431, 2023). "Similarly, cardiac Parkin deletion or expression of Mfn2 AA (a mutant that hinders Parkin mitochondrial translocation) caused cardiomyopathy and mortality in mice by impairing the replacement of fetal cardiomyocyte mitochondria by mature adult mitochondria." (PMID 37821940, 2023). "This points to a feasible pathogenic mechanism of cardiomyopathy in IDM because higher expression of MFN2 during cardiac development could contribute to a decreased number of cardiomyocytes, secondary hypertrophy, and impaired diastolic and systolic function." (PMID 31242551, 2019). "Cardiac ablation of both Mfn1 and Mfn2 causes a mild cardiomyopathy." (PMID 28190190, 2017). "However, as Mfn2 is a crucial regulator of mitochondrial morphology as well as of mitochondrial-ER junctions, a causative role for altered Mfn2-mediated mitophagy in cardiomyopathy remains to be established." (PMID 26611876, 2016). "The genes for mitobiogenesis and mitophagy were downregulated when both Mfn1 and Mfn2 were removed in midgestational and postnatal cardiac myocytes, and the mice went on to develop cardiomyopathy and died within 16 days of birth." (PMID 37821940, 2023). "In conclusion, the current findings point to MFN2 and potentially other mitophagy signaling pathways as candidate genetic modifiers of cardiomyopathy." (PMID 37910431, 2023). "The overall MFN2 R400Q MAF of 0.0015 in cardiomyopathy, when compared to MAF of 0.000074 from the gnomAD database, represents ~20-fold over-representation in the combined heart disease populations (p<0.00001)." (PMID 37910431, 2023). "While excessive cardiomyocyte apoptosis can be seen in cardiomyopathies, miR-675 downregulation also results in increased expression of MFN2, which is contrary to what many studies observed in DM." (PMID 37719978, 2023).
cardiomyopathy (continued). "Specifically, among the two, MFN2 seems to be more important for mitochondrial homeostasis, since its elimination leads to early CH and cardiomyopathy." (PMID 36187489, 2022). "In adult cardiomyocytes, elimination of MFN1 and MFN2 induce mitochondrial dysfunction and fragmentation, leading to CH and cardiomyopathy." (PMID 36187489, 2022). "In the same line, cardiomyopathy is induced by the removal of MFN2, preventing Parkin recruitment into damaged mitochondria." (PMID 36187489, 2022). "In contrast, in another study investigating the role of mitochondrial dynamics in the pathogenesis of diabetic cardiomyopathy, imbalanced mitochondrial dynamics is considered to be the major reason for cardiomyopathy after Mfn2 knockdown." (PMID 34804365, 2021). "PINK1-dependent mitophagy has been linked to this reprogramming and mice expressing a cardiac specific mitofusin-2 mutation, which cannot be phosphorylated by PINK1, developed progressive cardiomyopathy and died by 7-8 weeks of age." (PMID 32420530, 2020). "Here we review the structural and functional properties of Mitofusin 2, highlighting its crucial role in several cell pathways, as well as in the pathogenesis of neurodegenerative diseases, metabolic disorders, cardiomyopathies, and cancer." (PMID 29491355, 2018). "Combined ablation of both Mfn1 and Mfn2 in the adult murine heart induces a lethal cardiomyopathy after several weeks, probably due to the mitochondrial fragmentation present in these hearts." (PMID 28190190, 2017). "In that work, expression of normal human Mfn2 rescued the cardiomyopathy induced by cardiomyocyte-specific RNAi suppression of Drosophila MARF." (PMID 22957060, 2012). "Additionally, nuclear genes like OPA1, Drp1, Mfn1, and Mfn2 regulate mitochondrial fusion and fission, and their altered expression disrupts mitochondrial morphology and dynamics, contributing to cardiomyopathy, arrhythmias, and overall cardiac dysfunction." (PMID 40416162, 2025). "Thus, the development of cardiomyopathy in Mfn2 Q/Q400 fetuses and neonates corresponds with signature abnormalities of myocardial metabolism." (PMID 37910431, 2023). "But, there has been reported that overexpression of MFN1 or MFN2 rescues cardiomyopathy." (PMID 38156294, 2023). "Indeed, conditional cardiomyocyte-specific Mfn2 knockout in mice resulted in cardiomyopathy, failure to recruit Parkin to depolarized mitochondria and defective mitophagy." (PMID 34114603, 2021). "Clearly, Mfn1 and 2 have distinct roles: a single Mfn1 allele and no Mfn2 expression in mice did not affect baseline cardiac function, whereas mice with a single cardiac Mfn2 allele and no Mfn1 expression developed cardiomyopathy at 8 weeks of age." (PMID 25652199, 2015). "Additionally, SGLT-2i can influence the mitochondrial fusion/fission proteins, such as Mitofusin-1 and Mitofusin-2, which may have potential in the treatment of cardiomyopathies and AF." (PMID 40004127, 2025). "Here, we determined that the rare mitofusin (MFN) 2 R400Q mutation is 15–20× over-represented in clinical cardiomyopathy, whereas this specific mutation is not reported as a cause of MFN2 mutant-induced peripheral neuropathy, Charcot–Marie–Tooth disease type 2A (CMT2A)." (PMID 37910431, 2023). "The lack of MFN2 in the short‐term can be protective by increasing cellular proliferation, and prolonged decrease in MFN2 may result in serious cardiomyopathy defects due to a loss of fusion." (PMID 38156294, 2023). "Second, the ablation of Mfn2 or Hsc70 results in the disassociation between mitochondria and LDs in both mouse hearts and cultured cardiomyocytes, leading to lipid accumulation and severe HFD‐induced cardiomyopathy." (PMID 38311582, 2024). "Of note, whether the observed cardiotoxicity in the absence of MFN2 is due to impaired mitophagy is not clear, as cardiomyopathy is not observed in Parkin knockout mice." (PMID 34114603, 2021).
cardiomyopathy (continued). "Furthermore, cardiomyocyte expression of human Mfn1 or Mfn2 rescued the cardiomyopathy observed in Drosophila with no expression of mitochondrial assembly regulatory factor (MARF), a Drosophila ortholog of mammalian Mfns." (PMID 25652199, 2015). "In parallel OCT studies, cardiomyocyte-specific suppression of dMfn depressed heart tube contractions (compared to tincΔ4-Gal4 controls); this cardiomyopathy was rescued by concurrent expression of wild-type Mfn2, but not mutant M393I or R400Q Mfn2 at both 1 and 4 weeks." (PMID 22957060, 2012).
type 2 diabetes (31 papers, 2008 to 2025). "One of the miRNAs identified by human skeletal muscle GWAS as being associated with type II diabetes, miR-106b, has been further investigated regarding its role in mitofusin-2 (MFN2) mediated mitochondrial dysfunction." (PMID 24369540, 2013). "Furthermore, acute knockdown of Mfn2 directly leads to impaired GSIS in islet, which highlights the possibility that decrease in Mfn2 expression due to JPH3 downregulation in beta cells might cause development of type 2 diabetes." (PMID 27336719, 2016). "On the basis of these observations, we propose that increased mitochondrial fusion caused by PGC-1β-induced Mfn2 contributes to a fully optimal mitochondrial activity in muscle and liver tissues, which may be defective in skeletal muscle of type 2 diabetic patients." (PMID 18974884, 2008). "In type 2 diabetes patients, a reduction in skeletal muscle Mfn2 expression has been observed, with Mfn2 levels correlating positively with insulin sensitivity." (PMID 39763653, 2024). "Expression of Mfn2 was reduced in skeletal muscle of obese and lean type 2 diabetic patients compared to lean insulin sensitive individuals." (PMID 38478198, 2024). "Altered activity of MFN2 was reported in the skeletal muscles of both obese subjects and type 2 diabetic patients." (PMID 33815291, 2021). "Previous reports have suggested that the mfn2 protein levels are reduced in the skeletal muscle of obese rats and type 2 diabetic patients." (PMID 30988232, 2019). "The observation that Mfn2 mRNA and protein expression was diminished in skeletal muscles of type 2 diabetics, as well as in obese patients and rats, initiated investigations into transcriptional regulators of Mfn2." (PMID 29068134, 2018). "It has been documented that mitochondrial fragmentation accompanied by suppressed Mitofusin 2 (Mfn2) expression occurs in obese or type 2 diabetes patients." (PMID 25908643, 2015). "The result is consistent with the mitochondrial networking fragmentation and decreased Mfn2 expression in muscles from patients with type 2 diabetes and obese humans." (PMID 25908643, 2015). "Interestingly, training did not change MFN2 expression, which is in contrast to the increase in MFN2 shown in type 2 diabetes patients and in hypertensive subjects of similar age and body composition following a high‐intensity training intervention." (PMID 33426802, 2021). "Finally, in humans with type 2 diabetes it was shown that protein levels of both MFN2 and OPA1 were reduced in skeletal muscle compared with obese control individuals." (PMID 33258025, 2021). "Indeed, decreased skeletal muscle mitochondrial size and Mfn2 expression was found in obesity and type 2 diabetes." (PMID 29538286, 2018). "Thus, it reverses the changes observed in PBMCs from type 2 diabetic patients, who are characterized by down-regulation of MFN2, PINK1, PARKIN, and LAMP-2 genes at the mRNA and protein level." (PMID 30356025, 2018). "In addition, skeletal muscle of obese subjects and type 2 diabetic patients also showed a reduced expression of Mfn2 mRNA and Mfn2 protein compared to lean subjects." (PMID 26834644, 2015). "Defective Mfn2 may also contribute to impaired mitochondrial function in the context of obesity and type 2 diabetes." (PMID 18974884, 2008). "For type II diabetes, AA can increase β-cell maturation by modulating the TNF-α/Mfn2 signaling pathway as well as up-regulating the expression of Mfn2 and Ucn3 proteins to achieve hypoglycemia." (PMID 41011581, 2025). "Furthermore, reduced mitochondrial size in muscle and decreased MFN2 expression was observed in mouse models of type 2 diabetes mellitus (T2DM) and obesity." (PMID 38812059, 2024). "Mfn2 repression was detected in the skeletal muscles of both obese and non-obese type 2 diabetic patients." (PMID 26834644, 2015).
type 2 diabetes (continued). "In keeping with the possibility that chronic exercise training failed to activate a mitochondrial oxidative response in young type 2 diabetes, acute exercise did not induce PGC-1alpha gene expression, and chronic exercise did not induce Mfn2 expression in early-onset type 2 diabetic patients." (PMID 29062026, 2017). "On the other hand, and in contrast to our hypothesis, men with type 2 diabetes had higher protein levels of ETC complex IV, MFN2, DRP1, Na+/K+ α1, Na+/K+ α2, and NHE1 compared to the nondiabetes counterparts." (PMID 33426802, 2021). "In prior publications, we reported that early-onset type 2 diabetic patients do not improve VO2max in response to an exercise intervention, and in parallel, acute exercise does not induce muscle PGC-1alpha gene expression, and chronic exercise does not induce muscle mitochondrial Mfn2 expression." (PMID 29062026, 2017).